MYC (MYC proto-oncogene, bHLH transcription factor)
Diseases named in the same sentence as MYC in open-access papers (continued):
Sharing a sentence is not in itself a finding about the gene and the disease.
neuroblastoma (continued). "Tissue specific conditional mycn knockout in neural progenitor cells during mouse development has demonstrated the importance of mycn for regulating neurogenesis, perhaps explaining the greater role of MYCN in neuroblastoma pathogenesis over c-MYC." (PMID 19997598, 2009). "Two pediatric LGAs harbored mutations in MYC, a well established oncogene homologue of NMYC, which is amplified and indicative of poor prognosis in pediatric neuroblastoma." (PMID 19924296, 2009). "To further analyze MYCN/c-MYC activity as well as differential regulation of MYCN/c-MYC target genes in neuroblastoma subtypes, we thought to define a comprehensive set of target genes directly regulated by MYCN and/or c-MYC in neuroblastoma cells." (PMID 18851746, 2008). "The polyclonal antibody against c-MYC also gave positive binding signals for a large set of target gene promoters in neuroblastoma cell lines with high MYCN that lack detectable c-MYC expression (SH-EPMYCN, IMR5/75 and Kelly)." (PMID 18851746, 2008). "Neuroblastoma cell lines with high expression of MYCN as a result of amplification lack c-MYC expression." (PMID 18851746, 2008). "In this study, we analyzed MYCN and c-MYC activity as reflected by the expression levels of a core set of direct MYCN/c-MYC targets in neuroblastoma subtypes." (PMID 18851746, 2008). "To further validate target gene regulation by MYCN/c-MYC in neuroblastoma cells, we performed ChIP-chip using a 244K oligonucleotide promoter microarray (Agilent)." (PMID 18851746, 2008). "Almost all 140 target gene promoters showed binding of MYCN and/or c-MYC in the six analyzed neuroblastoma cell lines as measured by ChIP-chip." (PMID 18851746, 2008). "Taken together, these results indicate that the genes from subgroups I and II represent a core set of target genes directly regulated by either MYCN or c-MYC in neuroblastoma cells dependent on which MYC protein is expressed." (PMID 18851746, 2008). "ChIP-chip experiments were performed with a monoclonal antibody against human MYCN and a polyclonal antibody against human c-MYC for each of the neuroblastoma cell lines." (PMID 18851746, 2008). "Here, we defined a core set of MYCN and c-MYC target genes by using oligonucleotide microarrays and a neuroblastoma cell line that allows conditional expression of MYCN or c-MYC." (PMID 18851746, 2008). "Whenever MYCN and c-MYC are co-expressed in neuroblastoma cell lines, c-MYC expression predominates." (PMID 18851746, 2008). "In addition to translocations, enhancer hijacking in neuroblastoma can originate from a focal amplification of active enhancers, which can in turn upregulate MYC expression." (PMID 39887412, 2026). "In this study, we reveal PA2G4 as a critical cofactor for both MYCN and c-MYC in neuroblastoma." (PMID 41002386, 2025). "This leaves open the possibility that in MYC-driven neuroblastoma, PA2G4 could also play a role, though further datasets will be needed to clarify this." (PMID 41002386, 2025). "This transition is tightly regulated by oncogenic drivers such as neuroblastoma-derived MYC (MYCN), which play a pivotal role in reprogramming gene expression and promoting metabolic reorganization to meet the increased biosynthetic demands of aggressive cancer cells." (PMID 41198652, 2025). "Moreover, PA2G4 elevates c-MYC protein levels in neuroblastoma cells by inhibiting its ubiquitin-mediated degradation." (PMID 41002386, 2025). "It is known that MYC–driven neuroblastoma has deregulated splicing." (PMID 40962798, 2025). "Similarly, MYC TF demonstrates significant enrichment in neuroblastoma cell lines, consistent with its well-established role in neural lineage cancers." (PMID 41279024, 2025).
neuroblastoma (continued). "Taken together, the findings suggest that MYC suppression, particularly in conjunction with C170 induces tumor cell immunity by disrupting multiple DNA damage repair pathways among other potential mechanisms in human neuroblastoma tumor cells." (PMID 40552293, 2025). "MYCN and c-MYC are critical driver oncogenes in several childhood cancers, including neuroblastoma." (PMID 41002386, 2025). "JMJD6 is required for neuroblastoma growth and facilitates MYC-mediated cellular transformation." (PMID 38488852, 2024). "Although we have identified a conserved interactome of JMJD6 in neuroblastoma cells, it remains to be determined whether it is neuroblastoma-specific and essential to MYC-driven cancers." (PMID 38488852, 2024). "In addition, high levels of the MYC target gene signature and low levels of the PRC2 target gene signature were associated with particularly poor outcome in 498 primary neuroblastoma tumors." (PMID 38992040, 2024). "In addition, in the transgenic MYCN mouse model of neuroblastoma, the chromosomal locus syntenic to human 17q is partially amplified, indicating that chromosome 17q is needed for MYC-mediated tumorigenesis." (PMID 38488852, 2024). "Importantly, SNRPD3 expression strongly correlated (R = 0.926) with the level of MYC-signature expression during neuroblastoma." (PMID 38049564, 2024). "Augmented MYC expression is responsible for aggressive behavior in other neuroblastomas." (PMID 38413795, 2024). "Whilst MYC amplification is very rare in neuroblastoma, our observations with CHLA-15 cells may have clinical relevance for some patients." (PMID 39313128, 2024). "Evidence links MYC hyperactivity to polyamine addiction and tumors like neuroblastoma may be particularly vulnerable to polyamine depletion therapeutics." (PMID 38200233, 2024). "The same synergy is found between MYC-driven neuroblastoma and Augα overexpression, suggesting that inhibitory antibodies might be effective for patient subgroups with ligand misregulation in addition to the potential benefits of ALK TKI treatment." (PMID 37892172, 2023). "To address this, we utilized three separate cancer cell lines we previously characterized to have intact molecular clocks that are disrupted by overexpressed MYC or N-MYC: SHEP N-MYC-ER (neuroblastoma), SKNAS N-MYC-ER (neuroblastoma), and U2OS MYC-ER (osteosarcoma)." (PMID 37639465, 2023). "Comparing models of various neuroectodermal tumors and normal fibroblasts revealed overexpression of MYC proteins phosphorylated at the degradation-promoting site T58 as a factor that predetermines vulnerability of MYC-driven neuroblastoma to mitoribosome inhibition." (PMID 37973789, 2023). "Here, we show that MYC-driven neuroblastoma cells rely on intact mitochondrial ribosome (mitoribosome) processivity and undergo cell death following pharmacological inhibition of mitochondrial translation, regardless of their multidrug/mitochondrial resistance and stem-like phenotypes." (PMID 37973789, 2023). "Therefore, knowing how much of this can be extended to N-MYC and N-MYC-amplified neuroblastoma is beneficial in determining the broad significance of WDR5 as a context-independent MYC cofactor." (PMID 37336886, 2023). "HDAC8 and c-MYC play important roles in promoting the growth and spread of neuroblastoma cells." (PMID 37894282, 2023). "MYCN was identified as a paralog of c-MYC in neuroblastoma cell lines and tumor tissues." (PMID 37046804, 2023). "However, when MYC-driven neuroblastoma mouse models were crossbred with mice that have an ALK gain-of-function mutation (ALK-F1178S), all the mice (98%) developed neuroblastoma within an average of 28 weeks." (PMID 37892172, 2023). "Our data indicate that the high c-MYC/N-MYC levels and extensive T58 phosphorylation, priming MYC proteins for rapid degradation upon the mitochondrial ISR, determine the propensity of MYC-driven neuroblastoma cells to cell death in response to inhibition of mitochondrial translation." (PMID 37973789, 2023).
neuroblastoma (continued). "Consequently, clock function in neuroblastoma can be subcategorized based on low/normal MYC expression (intact clock) versus MYC amplification (clock disrupted)." (PMID 37262074, 2023). "Furthermore, miR-665 has been found to activate cell death and increase the number of cells in G1 phase and decrease the cell number in S phase by targeting HDAC8 and c-MYC, reducing the malignancy of mouse neuroblastoma." (PMID 37894282, 2023). "Thus, the attenuated cap-dependent protein synthesis and enhanced proteasomal degradation upon mitochondrial stress-activated ISR are the major mechanisms causing the downregulation of short-lived oncoproteins, including MYC proteins in neuroblastoma cells." (PMID 37973789, 2023). "Moreover, the use of CBL0137 inhibited the FACT/MYC positive feedback loop and increased apoptosis in neuroblastoma tumors." (PMID 36691066, 2023). "Although neuroblastoma is strongly associated with altered ALK signaling, ALK gain-of-function mice develop sympathetic ganglia hyperplasia and not cancer, and additional key triggers are necessary for cancer development, typically MYC amplification." (PMID 37892172, 2023). "Pediatric neuroblastomas and PPGLs are characterized by a high degree of heterogeneity in disease presentation associated with distinct differentiation stages, affected by HIF and MYC signaling pathways." (PMID 37361539, 2023). "In view of MYC/N similarity and strongly associated expression of IGF2BP1 and MYCN in neuroblastoma, we hypothesized that MYCN promotes IGF2BP1 transcription as well." (PMID 37246217, 2023). "Mechanistically, inhibiting mitoribosomes induced the mitochondrial stress-activated integrated stress response (ISR), leading to downregulation of c-MYC/N-MYC proteins prior to neuroblastoma cell death, which could be both rescued by the ISR inhibitor ISRIB." (PMID 37973789, 2023). "We demonstrate that disruption of mitochondrial proteostasis by mitoribosome inhibitors activates integrated stress response (ISR), in part via OMA1, which leads to c-MYC/N-MYC downregulation and cell death preferentially in neuroblastoma cells that rely on elevated MYC proteins." (PMID 37973789, 2023). "Based on these findings, we propose mitochondrial translation as a novel synthetic lethal target that might be exploited to overcome multidrug resistance in MYC-driven neuroblastoma." (PMID 37973789, 2023). "In pediatric neuroblastoma xenograft models, 99 can slow tumor growth accompanied by reduced c-MYC, loss of BRD4 and increased HEXIM1, with no significant toxicity." (PMID 37142850, 2023). "Furthermore, brequinar treatment was shown to reduce the expression of MYC targets in 3 neuroblastoma models in vivo." (PMID 35943801, 2022). "Moreover, the PTBP1 and hnRNPA1 expression in glioma and neuroblastoma is regulated by MYC, a protein which is often overexpressed in cancer and can impair alternative splicing." (PMID 36230624, 2022). "A report pointed out that c-MYC is a transcription factor of PRPS1 in neuroblastoma." (PMID 36203561, 2022). "As we have previously reported, there are also neuroblastomas overexpressing MYC protein." (PMID 35053227, 2022). "Erastin-induced cell death increased with MYC(N) activity score in neuroblastoma cell lines, was associated with decreased GSH and reduction of the GSH reduced-to-oxidized ratio and could be prevented by providing either GSH or Fer-1." (PMID 35484422, 2022). "The over-expression of UTP18 in neuroblastoma promotes the expression of VEGF, Bcl-2, HIF1α, and c-MYC, improves the adaptability of tumor cells to environmental stress, and reduces the death of neuroblastoma cells after exposure to hydrogen peroxide, hypoxia or glucose deprivation." (PMID 35265610, 2022). "MYC overexpression is seen in a number of high-risk neuroblastoma patients (~10%) without MYCN amplification." (PMID 36185250, 2022). "We have shown that EZH2 plays an essential role in MYC(N) stabilization in neuroblastoma cells." (PMID 35013218, 2022).
neuroblastoma (continued). "This approach is also intriguing in light of our recent demonstration that high expression of the TCA cycle transferase DLST contributes to tumor development in multiple MYC-driven cancers, such as T-ALL, high-risk neuroblastoma, and triple-negative breast cancer (TNBC)." (PMID 35740646, 2022). "Moreover, the closely related c-myc transcription factor (MYC) has been established as a potent oncogene in an additional subset of neuroblastoma (approximately 10% of cases)." (PMID 35943801, 2022). "By contrast to BE2C and NGP cells, which became blocked in G1 phase, NBL-S and SKNAS cells treated with ATRA continued to enter S phase and progress through the cell cycle, consistent with the continued cell proliferation by these MYCN- or MYC-hijacked neuroblastoma cell lines." (PMID 34669465, 2021). "Using neuroblastoma as a model, we have therefore investigated the hypothesis that MYC-activated tumours could spread oncogenic signals to other body and tissue compartments via regulation of EVs protein cargo." (PMID 34847775, 2021). "The dependency of neuroblastoma on RBM39 is consistent with the concept that RNA splicing may be an “Achilles’ heel” of MYC-driven cancer." (PMID 34788094, 2021). "We also demonstrate that E2F target genes can act as biomarkers for sensitivity to KDM6B inhibitors in neuroblastoma and that this may well be predictive for other MYC-driven tumors." (PMID 34893606, 2021). "Collectively, these data indicate that neuroblastoma has an inordinate dependency on RBM39-mediated RNA splicing, which may represent a vulnerability in MYC-driven high-risk neuroblastoma." (PMID 34788094, 2021). "Thus, high levels of expression of either MYC or MYCN due to translocations hijacking next to the HAND2 super-enhancer produce neuroblastoma cells that are resistant to the effects of ATRA in inducing neuroblastoma cell differentiation." (PMID 34669465, 2021). "The high levels of DCAF15 and RBM39 dependence in neuroblastoma might make indisulam especially efficacious against this MYC-driven cancer." (PMID 34788094, 2021). "It would be beneficial to understand whether such a role also involves USP7 activity to deubiquitinate N-MYC especially in neuroblastoma with N-MYC amplification or antagonize TRIM32-mediated MYC ubiquitination and whether USP7 deubiquitinates c-MYC as well." (PMID 34178666, 2021). "We therefore hypothesized that mouse neuroblastomas driven by MYC will have a dependency on RBM39 analogous to human neuroblastoma." (PMID 34788094, 2021). "We reasoned that indisulam might be an effective agent for targeting the splicing program in MYC-driven neuroblastoma by degrading RBM39." (PMID 34788094, 2021). "We further validated these findings by stable expression of two different short hairpin RNAs (shRNAs) designed to target RBM39 in four different neuroblastoma models, all of which are MYC-driven as a result of either MYCN amplification (BE2C, KELLY, and SIMA) or C-MYC overexpression (SK-N-AS)." (PMID 34788094, 2021). "Indeed, specific subgroups of patients are more dependent on CDK7 (triple-negative breast cancer) and/or CDK9 (MYC-driven neuroblastoma)." (PMID 34344865, 2021). "The favourable toxicity profile of Prozac suggests that long-term treatments might be implemented in children with MYC/CKS1high neuroblastomas." (PMID 31900399, 2020). "Likewise, blockade of essential amino acid transport triggers the GCN2‐eIF2α‐ATF4 pathway and inhibits neuroblastoma tumor growth, which is concomitant with attenuated translation of MYC and MYCN mRNAs." (PMID 32310340, 2020). "Amplification of MYCN or constitutive upregulation of MYC protein is observed in approximately half of high-risk tumors; TAMs play a role as inducers of MYC expression in neuroblastomas lacking independent oncogene activation." (PMID 32244473, 2020). "High-risk MYCN non-amplified neuroblastoma often have an increased Wnt activity which contributes to its high aggressiveness by inducing c-MYC expression." (PMID 33585251, 2020).
neuroblastoma (continued). "In conclusion, we demonstrated that high c-MYC expression independent of genomic amplification is associated with disease progression in neuroblastoma." (PMID 32409685, 2020). "In this study, we investigated whether Prozac could be used to induce stabilisation of p27Kip1 and growth arrest/apoptosis of MYC-expressing neuroblastoma cells in vitro and in vivo." (PMID 31900399, 2020). "Our data revealed that ALDH1A1 and ALDH1A3 mRNA expression positively correlates with c-MYC gene expression in the neuroblastoma patient samples, and siRNA-mediated c-MYC knockdown inhibited expression of ALDH1A2 and ALDH1A3 genes in the MYCN-amplified neuroblastoma cells." (PMID 32483461, 2020). "High-risk, MYCN single copy neuroblastomas often express MYC as the oncogenic driver while MYCN is not expressed in these cells." (PMID 33585251, 2020). "Therefore, the role of ATF4 in neuroblastoma cells with elevated MYC varies depending on the condition." (PMID 32310340, 2020). "Here we report a novel pathway of MYC transcriptional activation that confers resistance to 13-cisRA, is frequently activated in PD neuroblastoma, and may serve as a therapeutic target." (PMID 32409685, 2020). "Thus, phosphorylation of OCT4 by MK2 transcriptionally activates MYC and this oncogenic pathway is upregulated in progressive disease relative to pre-therapy neuroblastomas." (PMID 32409685, 2020). "Here, we present chromatin immunoprecipitation sequencing (ChIP-Seq) data for the oncogenic transcription factors, MYCN and MYC, as well as regulatory histone marks H3K4me1, H3K4me3, H3K27Ac, and H3K27me3 in ten commonly used human neuroblastoma-derived cell line models." (PMID 32286315, 2020). "A recent study has showed that active MYC could preferentially upregulate LAT3 among many other SLC transporters in neuroblastoma cells, and that inhibition of LAT3 would in turn downregulate MYC mRNA levels." (PMID 31345230, 2019). "Furthermore, the previously reported 51 MYC target genes in neuroblastoma tumors were significantly down-regulated as MYCN knockdown." (PMID 31396265, 2019). "Therefore, a potential connection between SYK and MYC in neuroblastoma is highly interesting and warrants further investigation." (PMID 30744170, 2019). "To test whether this function of MYC is conserved for its different isoforms, we repeated the 4sU sequencing experiment in SH-EP neuroblastoma cells that express a MYCN-estrogen receptor chimeric protein." (PMID 30928206, 2019). "It is interesting to note that MYC protein overexpression was associated with around 30% of High MKI neuroblastomas without MYCN amplification." (PMID 29464082, 2018). "Furthermore, several studies have shown that aberrant ALK signaling in neuroblastoma cells regulates MYC and MYCN transcriptional initiation and protein stability." (PMID 29507657, 2018). "We hypothesized that Bt2cAMP inhibited neuroblastoma cell growth by inducing suppressor miRNAs targeting c-MYC and HDAC8." (PMID 30237861, 2018). "c-MYC regulates cell proliferation, apoptosis, and cellular metabolism, represses suppressor miRNA expression, and is involved in tumorigenesis in many cancers, including neuroblastoma." (PMID 30237861, 2018). "Detailed analysis remains to be carried out on cooperative binding by different network heterodimers, but initial work supports the idea that MYCN-MAX and MLXIP-MLX can co-occupy the TXNIP promoter region and act to cooperatively augment TXNIP expression in MYC-driven neuroblastoma." (PMID 30054853, 2018). "However, our previous work demonstrated that Wnt3a/Rspo2 treatment of some neuroblastoma cell lines can, paradoxically, decrease c-MYC and MYCN proteins." (PMID 29505958, 2018). "Highly aggressive MYC-driven neuroblastoma is defined by increased c-MYC and/or MYCN expression." (PMID 30237861, 2018).